ERAL1 (Era like 12S mitochondrial rRNA chaperone 1)
Description:
Probable GTPase that plays a role in the mitochondrial ribosomal small subunit assembly. Specifically binds the 12S mitochondrial rRNA (12S mt-rRNA) to a 33 nucleotide section delineating the 3' terminal stem-loop region. May act as a chaperone that protects the 12S mt-rRNA on the 28S mitoribosomal subunit during ribosomal small subunit assembly.
Synonyms: H-ERA; CEGA; HERA-B; ERA; ERA-W; ERAL1A; ERAL1B; HERA-A; PRLTS6
Tractability: Small molecule: a structure with a bound ligand is known. Antibody: UniProt places it where antibodies can reach, with medium confidence. PROTAC: ubiquitination databases record sites on it; its protein half-life has been measured.
Gene: Protein-coding gene on chromosome 17 (28,855,009 to 28,861,067, forward strand). Ensembl gene ENSG00000132591.
Subcellular location: Mitochondrion matrix; Mitochondrion inner membrane
Subcellular location (Human Protein Atlas): Mitochondria; Cytosol
Pathways (Reactome):
Metabolism of proteins: Mitochondrial ribosome-associated quality control; Mitochondrial translation elongation; Mitochondrial translation initiation; Mitochondrial translation termination
Gene Ontology:
Molecular function: protein binding; ribosomal small subunit binding; RNA binding; RNA folding chaperone; rRNA binding; GTP binding
Biological process: mitochondrial small ribosomal subunit assembly; ribosomal small subunit assembly; RNA folding
Cellular component: cytosol; mitochondrial matrix; mitochondrion; mitochondrial inner membrane
Genetic constraint (gnomAD): Loss-of-function variants: 36 observed, 56.35 expected, observed/expected ratio (o/e) 0.64, 90% interval 0.49 to 0.84. The upper end of that interval is the gene's LOEUF score, 0.84, which puts it in group 3 of 6, group 1 being the genes least tolerant of losing a copy. Missense variants: 512 observed, 570.04 expected, observed/expected ratio (o/e) 0.9, 90% interval 0.83 to 0.97. Synonymous variants: 215 observed, 225.98 expected, observed/expected ratio (o/e) 0.95, 90% interval 0.85 to 1.07.
Homologues: Orthologues: chimpanzee ERAL1 (99% identical), macaque ERAL1 (94% identical), guinea pig ERAL1 (81% identical), pig ERAL1 (79% identical), rat Eral1 (79% identical), rabbit ERAL1 (78% identical), mouse Eral1 (78% identical), dog ERAL1 (75% identical), tropical clawed frog eral1 (53% identical), zebrafish eral1 (44% identical), Caenorhabditis elegans eral-1 (21% identical), Drosophila melanogaster CG7488 (18% identical). Paralogues in human: GTPBP3 (18% identical).
Diseases named in the same sentence as ERAL1 in open-access papers:
ERAL1 is named in the same sentence as 10 diseases in open-access papers, as found by Europe PMC text mining. Sharing a sentence is not in itself a finding about the gene and the disease. The quoted sentences say what the papers report.
Perrault syndrome (9 papers, 2017 to 2025). Perrault syndrome (PS) is characterized by the association of ovarian dysgenesis in females with sensorineural hearing impairment. "Again, ERAL1 accumulation appears to be particularly relevant, given that ERAL1 mutations can trigger Perrault syndrome." (PMID 38927630, 2024). "In human cells, both ERAL1 knockdown and the Perrault syndrome N236I mutation significantly destabilized the mitochondrial SSU, impacting the mitochondrial protein synthesis and respiration." (PMID 37860580, 2023). "The selective impact of CLPXP on mtLSU was surprising, because Perrault syndrome is triggered by mutant HARS2/LARS2/ERAL1, all of which are associated with the mtSSU." (PMID 38139332, 2023). "The N236I mutation in the G4-motif of human ERAL1 causes the Perrault syndrome (sensorineural deafness and ovarian dysgenesis) in humans." (PMID 37860580, 2023). "The positive and negative regulatory mechanisms described in this section show that ERAL1 homeostasis is essential in mammalian cells as both ERAL1 deficiency and overproduction may be deleterious to mitochondrial translation, resulting in severe downstream effects, such as the Perrault syndrome." (PMID 37860580, 2023). "By contrast, RCCL1V3 knockdown significantly reduced the overall abundance of ERAL1 and the mitochondrial SSU and severely impacted the protein synthesis in the organelle, like it happened in the Perrault syndrome patient with the ERAL1N236I mutation." (PMID 37860580, 2023). "The connection between ERAL1 and CLPP is especially intriguing, since CLPP is also associated with the Perrault syndrome." (PMID 37860580, 2023). "In the heatmap among DNA/RNA processing factors, the early and consistent accumulation of mitochondrial factors was evident, including PEO1, ERAL1, and HARS2, whose mutations are known to trigger Perrault syndrome with ovarian germ cell failure." (PMID 36611846, 2022). "Ouridentification of ERAL1 as a Perrault syndrome gene further ties CLPP and ERAL1 together, asmutations in either of them lead to similar pathology in humans." (PMID 28449065, 2017). "Pathogenic/likely pathogenic variants in HARS2, CLPP, LARS2, TWNK, ERAL1, and PROPR may cause Perrault syndrome-related OD." (PMID 38812815, 2024).
breast carcinoma (7 papers, 2011 to 2022). "However, ERAL1 is involved in the formation of the 28S small mitochondrial ribosomal protein (MRPS28) and that protein has been shown to be involved with breast cancer proliferation and metastasis." (PMID 35902644, 2022). "Finally, DHRS13, ERAL1, and SLC9A3R2 could predict treatment response and survival; however, there are no reports related to breast cancer and its possible function in this disease." (PMID 36338974, 2022).
viral infections (2 papers, 2024 to 2026). "Additionally, ERAL1 can promote the RIG-I-like receptor signaling pathway to inhibit viral infections." (PMID 39351238, 2024).
colon carcinoma (1 paper, 2021). "This study sheds a light for elucidating the berberine-related regulatory signaling pathways in colon cancer, and suggests that ERAL1 and several mitochondrial ribosomal proteins might be promising therapeutic targets for colon cancer." (PMID 33806918, 2021). "Finally, GTPase ERAL1 and mitochondrial ribosomal proteins including MRPL11, 15, 30, 37, 40, and 52 were identified as hub proteins of berberine-treated colon cancer cells." (PMID 33806918, 2021). "Moreover, GTPase ERAL1 and mitochondrial ribosomal proteins MRPL11, 15, 30, 37, 40, and 52 have great potential to serve as potential therapeutic targets for colon cancer treatment." (PMID 33806918, 2021). "Finally, the GTPase ERAL1, mitochondrial ribosomal proteins ERAL1, MRPL11, MRPL15, MRPL30, MRPL37, MRPL40, and MRPL52 were determined to be hub proteins with a commonly down-regulated trend in four berberine-treated colon cancer cell lines." (PMID 33806918, 2021). "However, no studies have been performed on the functions of ERAL1 in colon cancer." (PMID 33806918, 2021). "In addition, we found that berberine could impair mitochondrial function by inhibiting mitochondrial protein, and GTPase ERAL1 as well as mitochondrial ribosomal proteins including MRPL11, 15, 30, 37, 40, and 52 have potential to serve as candidate targets of berberine in colon cancer cells." (PMID 33806918, 2021).
hearing loss (1 paper, 2023). "A homozygous missense variant in ERAL1 was associated with disrupted mitochondrial function, sensorineural hearing loss and ovarian dysgenesis." (PMID 37148394, 2023).
Infertility (1 paper, 2017). "Finally, we performed RNAiexperiments in the nematode C. elegans to demonstrate the role of ERAL1 infertility." (PMID 28449065, 2017).
ERAL1 also shares sentences with these, for which no sentence is quoted: tumor (2 papers); glioblastoma (1); infection (1); lymph node (1).